CSF1 (colony stimulating factor 1)
Diseases named in the same sentence as CSF1 in open-access papers (continued):
Sharing a sentence is not in itself a finding about the gene and the disease.
endometrial cancer (10 papers, 1996 to 2024). Primary or metastatic malignant neoplasm involving the endometrium (mucous membrane that lines the endometrial cavity). "Interestingly, CSF-1 is a growth factor associated with the histopathological grades of the endometrial carcinoma and plays a role in carcinogenesis, tumorigenesis, and metastasis in other cancers." (PMID 35804859, 2022). "In endometrial cancer, tumor cells drove macrophage infiltration via CSF-1 secretion, and CSF-1 silencing reduced the migratory ability of macrophages." (PMID 38254773, 2024). "The results show that the interaction between CSF-1 and its receptor plays an important role in promoting macrophage infiltration and endometrial cancer progression." (PMID 34729112, 2021). "For example, co-expression of CSF-1 and its receptor can be found in 50% of late stage breast and 70% of endometrial cancers." (PMID 22353646, 2012). "It should be noted that increased levels of circulating CSF-1 in human patients with breast, ovarian and endometrial cancer is correlated with poor prognosis." (PMID 19668347, 2009). "CSF-1 secreted by endometrial cancer cells promotes the migration and proliferation of macrophages." (PMID 34729112, 2021).
lung adenocarcinoma (10 papers, 2013 to 2025). A carcinoma that arises from the lung and is characterized by the presence of malignant glandular epithelial cells. "In the context of lung adenocarcinoma, lncRNA LARRPM restricts CSF1-mediated M2 macrophage polarization by guiding TET1 to the CSF1 promoter; as a result, DNA methylation of CSF1 promoter increases, and the transcription is repressed." (PMID 37637063, 2023). "Furthermore, macrophage progenitor cells accumulated in the splenic red pulp of a cancer-bearing mouse model with genetically developed lung adenocarcinoma, and macrophages were mobilized in the tumor by tumor-derived factors CCL2 and CSF-1." (PMID 37553633, 2023).
osteosarcoma (10 papers, 2014 to 2025). A usually aggressive malignant bone-forming mesenchymal neoplasm, predominantly affecting adolescents and young adults. "Osteosarcoma cells polarized macrophages to an M2 phenotype via CSF1 and CSF1R, and interactions between LYVE1+ and angiogenic macrophages through CCL2 and CCR1 promoted a proangiogenic niche and inflammatory responses." (PMID 40647416, 2025). "Osteosarcoma cells also secrete colony-stimulating factor-1 (CSF1), which can stimulate ERK1/2 phosphorylation in bone marrow-derived macrophages (BMDMs), polarize BMDMs toward an M2 (TAM-like) phenotype, and promote BMDM chemotaxis." (PMID 39359731, 2024). "Osteosarcoma cell lines with overexpression of CSF-1R ligands CSF-1 and IL-34 have a propensity to polarize TAMs to the M2 subtype, resulting in more progressive disease in a murine osteosarcoma model." (PMID 32961800, 2020). "Additionally, CSF1, expressed on osteosarcoma cells, interacts with CSF1R, which is highly expressed in the macrophages." (PMID 40647416, 2025). "Additionally, a paracrine loop of CSF1 secreted from osteosarcoma cells in the tumor niche continuously activates M2-TAM, leading to the differentiation and polarization of macrophages, as well as aggravates tumorigenesis." (PMID 39359731, 2024).
triple-negative breast carcinoma (10 papers, 2017 to 2025). An invasive breast carcinoma which is negative for expression of estrogen receptor (ER), progesterone receptor (PR), and human epidermal growth factor receptor 2 (HER2). "Taken together, these results suggest that a novel regulatory element ~30 kb upstream of the CSF1 gene is more highly transcribed in triple-negative breast cancer patients and is associated with increased expression of CSF1 mRNA." (PMID 35406623, 2022). "In triple negative breast cancer, the cross-talk between tumor cells and MSCs, caused the production of macrophage colony-stimulating factor 1 (CSF1) that recruited in the TME, tumor-associated macrophages (TAMs) and myeloid-derived suppressor cells (MDSCs)." (PMID 29069870, 2017). "In patients with advanced triple negative breast cancer, the combination of a CSF-1 monoclonal antibody with gemcitabine and carboplatin showed comparable anti-tumor activity and progression-free survival compared to gemcitabine and carboplatin alone." (PMID 40646332, 2025). "This work implicates a role for the CSF1 enhancer in the progression of triple-negative breast cancer and potentially other cancer types, highlighting the eRNA transcripts and associated downstream genes as potential targets for the therapeutic intervention." (PMID 35406623, 2022). "For instance, exosomes bearing CSF-1 from triple-negative breast cancer cells can induce monocyte differentiation towards proinflammatory macrophages with IFN response, partly through the cGAS/STING signaling pathway, and are associated with better clinical outcomes." (PMID 37670933, 2023). "The evidence collected thus far suggests that the CSF1 enhancer is specific to triple-negative breast cancer, may be conferring growth advantages to tumor cells, and a reduction in CSF1 leads to changes in the expression of several other genes." (PMID 35406623, 2022). "A recent study has identified a novel putative enhancer located upstream of colony-stimulating factor 1 (CSF1), a highly expressed gene in triple-negative breast cancer cells." (PMID 37509229, 2023). "For example, both miR-149 in triple-negative breast cancer (TNBC) and miR-148b in HCC have been demonstrated to target colony-stimulating factor-1 (CSF-1) miRNAs." (PMID 34064331, 2021).
Cirrhosis (9 papers, 2016 to 2025). A chronic disorder of the liver in which liver tissue becomes scarred and is partially replaced by regenerative nodules and fibrotic tissue resulting in loss of liver function. "Our study found increased levels of HGF, CSF1, and uPA—three markers believed to be associated with liver regeneration—to be associated with greater odds of developing clinical cirrhosis." (PMID 34782638, 2021). "HGF, SLAMF1, CSF1, and uPA were associated with cirrhosis among those diagnosed ≥ 6.57 years after serum collection." (PMID 34782638, 2021). "Furthermore, colony-stimulating factor-1-induced BMMs were reported to have a therapeutic effect on CCl4-induced cirrhosis in mice." (PMID 40430042, 2025). "Similarly, CSF1 has also been reported to be elevated in patients with acute liver injury as well as those diagnosed with cirrhosis and HCC22." (PMID 34782638, 2021).
Cognitive impairment (9 papers, 2011 to 2025). Abnormal cognition is characterized by deficits in thinking, reasoning, or remembering. "In this study, we investigated the levels of the macrophage growth factors IL-34 and CSF-1 in three biofluids at different stages of cognitive impairment and found higher levels of IL-34 in saliva from AD patients compared with controls and subjects with SCI." (PMID 40389754, 2025). "In summary, H2O2‐treated astrocytes secrete high concentrations of CSF‐1, leading to increased apoptosis and decreased hippocampal neurogenesis, ultimately resulting in cognitive impairment in 20‐month‐old rats." (PMID 40304412, 2025). "We analyzed the levels of IL-34 and CSF-1 in saliva, CSF, and plasma in participants with different stages of cognition impairment." (PMID 40389754, 2025). "Therefore, we aimed to investigate the salivary levels of IL-34 and CSF-1 in different stages of cognitive impairment, and in relation to periodontal status." (PMID 40389754, 2025). "The gene expression of CSF-1 and IL-34 in brain tissue during health and cognitive impairment remains to be fully elucidated, however one study reported increased gene expression of CSF-1 and CSF-1R, and reduced expression of IL-34 in human brain samples from AD patients." (PMID 40389754, 2025).
depression (9 papers, 2018 to 2025). "Macrophage colony-stimulating factor 1 (M-CSF) reached higher levels in patients with psychotic depression during early remission, which may be indicative of a sustained macrophage activation and a pronounced innate immune response within this group." (PMID 39355377, 2024).
endometriosis (9 papers, 2013 to 2025). The growth of functional endometrial tissue in anatomic sites outside the uterine body. "Our data demonstrated that peritoneal fluid from women with endometriosis contained a significantly higher percentage of CSF-1 than that from control subjects." (PMID 35260161, 2022). "Does the cytokine CSF-1 induce monocytes to differentiate into macrophages with a DC-SIGN+ phenotype in endometriosis?" (PMID 35260161, 2022). "The level of the CSF-1 cytokine in the PF of endometriosis patients was higher than that in the PF of controls." (PMID 35260161, 2022). "CSF-1 has been found to accumulate in the lesions and PF of endometriosis patients, and CSF-1 induces THP-1-derived macrophages to polarize toward a CD169+ DC-SIGN+ phenotype." (PMID 35260161, 2022). "Further study of the mechanism and biological activities of CSF-1-induced DC-SIGN+ macrophages will enhance our understanding of the physiology of endometriosis." (PMID 35260161, 2022). "This study provides a framework for developing CSF-1-based in vitro protocols to generate therapeutic macrophages for clinical use to regulate the immune environment of endometriosis." (PMID 35260161, 2022). "Overall, the aim of our study was to prove that CSF-1 induces monocytes to differentiate into macrophages with a CD169+ DC-SIGN+ phenotype in endometriosis and that this macrophage phenotype can influence the differentiation of T cells." (PMID 35260161, 2022). "Mounting evidence suggests that CSF-1 is increased in endometriosis and is conducive to the formation of endometriotic lesions." (PMID 31727934, 2019). "Nerves in the endometriosis lesion release chemicals like colony-stimulating factor-1 (CSF-1), chemokine ligand 2 (CCL-2), leukemia inhibitory factor (LIF), and pancreatitis-associated protein III (PAP-III), which induce the migration of macrophages toward the nerve ending." (PMID 40747182, 2025). "CSF-1 was primarily secreted from ectopic lesions and peritoneum in mice with endometriosis." (PMID 35260161, 2022). "The principal source of CSF-1 may be ectopic lesions in mice with endometriosis." (PMID 35260161, 2022). "The inference of our findings, that microbiota may regulate the prevalence of CSF1‐independent F4/80loMHCII+ macrophages, may be similarly important in the interplay between microbiota and inflammatory diseases of the peritoneal cavity, for example, as may occur during endometriosis." (PMID 35568024, 2022). "Through interactions between PMCs and ESCs in this co-culture system, several endometriosis-related genes including CD44, ERK, CSF-1, and c-Met were upregulated in both PMCs and ESCs." (PMID 31636643, 2019). "Although the protein expression level of CSF-1R in the ectopic lesions of endometriosis patients was not different from that in the eutopic endometrium of endometriosis patients and the normal endometrium, the gene expression level of CSF-1 was significantly higher in these lesions." (PMID 35260161, 2022).
liver fibrosis (9 papers, 2016 to 2025). "CSF1 drives the maturation of Ly6CHi into Ly6CLow monocytes, which have previously been associated with resolution of liver fibrosis, and their subsequent differentiation into macrophages." (PMID 35169835, 2022). "It has been reported that CSF-1-induced murine bone marrow cell-derived Mfs intravenously administered from tail vein ameliorate carbon tetrachloride (CCl4)-induced liver fibrosis." (PMID 39856797, 2025). "In overview, these studies indicate that CSF1-Fc treatment has the potential to initiate liver fibrosis resolution, but evaluation of chronic treatment regimens with existing reagents in mice is compromised by an anti-drug response." (PMID 35169835, 2022). "To model treatment of established liver disease in humans following removal of the primary stimulus, we tested the impact of CSF1-Fc treatment on liver fibrosis resolution after TAA cessation." (PMID 35169835, 2022). "It is already well-established that CSF-1 Mf is highly effective against liver fibrosis." (PMID 39856797, 2025). "Some of these genes have been previously implicated in liver fibrosis (Serpine133, Tgm234), while role of others (Cd14, Marco, Csf1) have not been investigated to date." (PMID 32398673, 2020). "On the other hand, the CSF1/IL34–CSF1R signaling axis activates hepatic macrophages and produces pro-inflammatory cytokines, thereby promoting hepatic fibrosis." (PMID 40539070, 2025). "The therapeutic capacity of IL-34 Mf for liver fibrosis seems consistent to, or at least not inferior to, that of CSF-1 Mf." (PMID 39856797, 2025). "Here, we tested the therapeutic potential of CSF1-Fc and the role of macrophages in resolution of liver fibrosis in a non-resolving model of chronic inflammatory liver injury." (PMID 35169835, 2022). "However, some of the earliest studies of CSF1 in disease models also showed the potential for exacerbation of inflammatory pathology, and macrophage depletion with anti-CSF1R or anti-CSF1 was previously shown to ameliorate development of toxin-induced liver fibrosis in mice." (PMID 35169835, 2022).
lupus nephritis (9 papers, 2015 to 2024). Glomerulonephritis in the context of systemic lupus erythematosus. "Another study identified that urinary colony-stimulating factor-1 levels were associated with disease activity, which was a potential biomarker to reflect the onset, recurrence and disease activity of lupus nephritis." (PMID 33081708, 2020). "In MRL/lpr mice, transient ischemic renal injury upregulates CSF-1 expression in renal tubular epithelial cells, leading to increased release of CSF-1 and subsequent expansion of M1 macrophages, accelerating the onset of lupus nephritis." (PMID 39224584, 2024). "CSF1 is involved in the pathogenesis of lupus nephritis in NZBWF1 mice." (PMID 37529109, 2023). "CSF1 is upregulated in renal tubular epithelial cells in response to renal injury stimuli and could mediate inflammatory damage and apoptosis in human mesangial cells in lupus nephritis." (PMID 37529109, 2023). "Elevated levels of CSF1 in serum, urine, and kidneys are correlated with the activity of lupus nephritis, and CSF1R inhibition could deplete macrophages and ameliorate kidney injury by decreasing proteinuria and blood urea nitrogen and improving renal histopathology." (PMID 35601837, 2022).
renal cell carcinoma (9 papers, 2019 to 2024). "In vitro and in vivo studies have confirmed that CSF1 promotes proliferation and reduces apoptosis in renal cell carcinoma." (PMID 35860566, 2022). "Binding co-expression of CSF1/CSF1R derived from renal cell cancer enhances cancer cell growth." (PMID 38287102, 2024). "In renal cell carcinoma (RCC), C1QB expression can influence CSF-1-induced macrophage migration and hamper their adhesion and chemotaxis." (PMID 36969247, 2023). "For instance, the CSF-1/CSF-1R axis could induce phosphorylation and activation of STAT3, which promotes cell survival and proliferation in renal cell carcinoma." (PMID 31565097, 2019). "When CSF-1 and CSF-1R are coexpressed in renal cell carcinoma and TEC aids in RCC survival and inhibition of apoptosis." (PMID 33414786, 2020).
Thrombocytopenia (9 papers, 1996 to 2025). A reduction in the number of circulating thrombocytes. "A similar pattern has been seen in mammals, including primates, where CSF1 treatment caused thrombocytopenia, but increased all the white cell populations." (PMID 25857347, 2015). "Similarly, CSF1 administration causes a transient thrombocytopenia, attributed to increased platelet clearance, which is resolved by an increase in platelet production." (PMID 39869647, 2025). "In the current study, we observed transient thrombocytopaenia, even with low-dose CSF1-Fc, but this was rapidly resolved." (PMID 35169835, 2022). "Transient thrombocytopaenia was the dose-limiting toxicity in initial human clinical trials of CSF1." (PMID 35169835, 2022). "In initial studies of infusion of CSF1 in human patients, the dose-limiting toxicity was thrombocytopenia, and we also observed reduced platelet numbers in mice and pigs treated with CSF1-Fc." (PMID 29351395, 2018).
diabetes (8 papers, 2010 to 2024). "In conclusion, melatonin reduced Leydig cell apoptosis induced by ERS and increased the secretion of the cytokine, CSF1, which improved the reduced spermatogenesis caused by diabetes." (PMID 30237484, 2018). "Consistent with the mRNA expression pattern, the CSF1 protein expression was downregulated in the testicular cells of the mice with diabetes and restored significantly in the long term melatonin treatment groups (P < 0.01)." (PMID 30237484, 2018). "Real-time PCR (RT-PCR) revealed that STZ-induced diabetes was associated with significantly up-regulated MCP-1 (Mcp1), CSF-1 (Csf1), ICAM-1 (Icam1), and VCAM-1 (Vcam1) expression in Nrf2+/+ and Nrf2−/− mice, and these changes in expression were reversed by digitoflavone in Nrf2+/+ mice only." (PMID 26205695, 2015).
giant cell tumor (8 papers, 2010 to 2024). A benign, intermediate, or malignant tumor that arises from the bone or soft tissue. "RNA-sequencing was performed on three tenosynovial giant cell tumors (TSGCT) in an attempt to elicit more information on the mechanisms of CSF1 expression in this tumor type." (PMID 24604026, 2014). "A randomised phase 3 trial for tenosynovial giant cell tumour with aberrantly expressing colony-stimulating factor 1 (CSF1) showed pexidartinib as CSF1R inhibitor could improve patient symptoms and functional outcomes." (PMID 32908485, 2020). "Clinically available drugs targeting CSF1 or CSF1R include pexidartinib, which repolarizes M2 macrophages and has demonstrated safety and activity in a phase 3 trial resulting in the first available systemic therapy available for tenosynovial giant cell tumors." (PMID 38612926, 2024). "We also investigated CSF1 IHC in giant cell-rich tumor (GCRT) and GCRT-like lesion, which occur in the bone and characteristically show the presence of osteoclast-like giant cell including giant cell tumor of bone, giant cell reparative granuloma, and aneurysmal bone cyst." (PMID 36320082, 2022).